ANGPTL5 (angiopoietin like 5)
Tractability: Antibody: UniProt places it where antibodies can reach, with high confidence; UniProt predicts a signal peptide or a membrane-spanning region; its Gene Ontology location is reachable by antibodies, with medium confidence.
Gene: Protein-coding gene on chromosome 11 (101,890,674 to 101,916,522, reverse strand). Ensembl gene ENSG00000187151.
Subcellular location: Secreted
Gene Ontology:
Molecular function: protein binding
Cellular component: extracellular matrix; extracellular region
Genetic constraint (gnomAD): Loss-of-function variants: 20 observed, 25.09 expected, observed/expected ratio (o/e) 0.8, 90% interval 0.56 to 1.16. The upper end of that interval is the gene's LOEUF score, 1.16, which puts it in group 5 of 6, group 1 being the genes least tolerant of losing a copy. Missense variants: 351 observed, 342.42 expected, observed/expected ratio (o/e) 1.03, 90% interval 0.94 to 1.12. Synonymous variants: 109 observed, 116.54 expected, observed/expected ratio (o/e) 0.94, 90% interval 0.8 to 1.1.
Homologues: Orthologues: chimpanzee ANGPTL5 (99% identical), macaque ANGPTL5 (97% identical), pig ANGPTL5 (91% identical), rabbit ANGPTL5 (91% identical), guinea pig ANGPTL5 (89% identical), dog ANGPTL5 (89% identical), tropical clawed frog angptl5 (59% identical), zebrafish angptl5 (49% identical). Paralogues in human: TNR (28% identical), FGG (26% identical), ANGPTL1 (26% identical), TNN (26% identical), ANGPTL2 (25% identical), TNXB (25% identical), FGL1 (25% identical), TNC (24% identical), ANGPTL3 (23% identical), ANGPT1 (23% identical), ANGPT2 (23% identical), ANGPTL7 (23% identical), and 13 more.
Diseases named in the same sentence as ANGPTL5 in open-access papers:
ANGPTL5 is named in the same sentence as 17 diseases in open-access papers, as found by Europe PMC text mining. Sharing a sentence is not in itself a finding about the gene and the disease. The quoted sentences say what the papers report.
diabetes (3 papers, 2019 to 2023). "Of these, ANGPTL5 is suggested to regulate triglyceride metabolism and is increased in obesity and diabetes." (PMID 32286392, 2020). "Further stratification on T2D status of patients showed that ANGPTL5 levels were higher in subjects diagnosed with pre-diabetes compared with non-T2D subjects, but lower than in subjects with T2D." (PMID 31396158, 2019). "Further analysis will be required to better understand the interaction between ANGPTL5 and other metabolic related biomarkers to shed more light on its role in diabetes and obesity." (PMID 31396158, 2019). "We also observed that subjects who were at risk of developing T2D, i.e., pre-diabetes, had higher levels of ANGPTL5 than those without T2D, but lower than those with T2D." (PMID 31396158, 2019). "Additionally, subjects with pre-diabetes and T2D had elevated ANGPTL5 levels." (PMID 31396158, 2019). "While ANGPTL5 has been suggested to be involved in TGL metabolism, its role in diabetes and obesity remains to be elucidated." (PMID 31396158, 2019). "We also reported higher ANGPTL5 levels in adolescents with obesity compared to adolescents without obesity and in adults with and without diabetes." (PMID 38189043, 2023). "As we have shown here, our data suggest that ANGPTL5 has an important role in obesity, TGL metabolism and T2D, and may be a possible indicator of a pre-diabetes state or metabolic syndrome." (PMID 31396158, 2019).
Obesity (3 papers, 2019 to 2023). Accumulation of substantial excess body fat. "Second, the cross-sectional design of the study did not allow us to establish causality and requires further investigation to establish the role of ANGPTL5 in the development of obesity and the nature of its association with Ox-LDL and HsCRP." (PMID 32286392, 2020). "Multinomial logistic regression showed that the odds of obesity and overweight was significantly associated with ANGPTL5 in univariable analysis and after adjusting for potential confounders." (PMID 32286392, 2020). "Third, we employed several statistical approaches to robustly show the association between ANGPTL5 and obesity." (PMID 32286392, 2020). "Further studies with larger populations are needed to confirm the role of ethnicity in the association between ANGPTL5 and obesity." (PMID 32286392, 2020). "The use of ANGPTL5 as a powerful diagnostic and prognostic tool in obesity and metabolic diseases needs to be further evaluated." (PMID 32286392, 2020). "First, to the best of our knowledge, this is the first study investigating the association between ANGPTL5 and obesity and biomarkers for CVD in adolescents." (PMID 32286392, 2020). "Here, we report the results of a cross-sectional study showing the association of ANGPTL5 plasma levels with obesity and T2D." (PMID 31396158, 2019). "In this study, we tested the hypothesis of a positive association between plasma ANGPTL5, and obesity, high sensitivity C-reactive protein (HsCRP) and oxidized low-density lipoprotein (Ox-LDL) in adolescents." (PMID 32286392, 2020). "We hypothesize that, like other ANGPTL proteins, plasma ANGPTL5 levels are positively associated with obesity, HsCRP, and Ox-LDL." (PMID 32286392, 2020). "This increase in ANGPTL5 was associated with an increased obesity risk." (PMID 32286392, 2020). "To cite an example, we reported a correlation between higher circulating ANGPTL5 levels and obesity, high sensitivity C-reactive proteins (hsCRP), and oxidized low-density lipoprotein (ox-LDL) in adolescents." (PMID 38189043, 2023). "Having seen a positive correlation between ANGPTL8 levels and adult obesity, and positive correlations between ANGPTL5 and obesity levels in Arab children, we were motivated to examine the ANGPTL8 levels in the context of adolescent obesity." (PMID 38189043, 2023). "This study was designed to investigate the expression levels of ANGPTL5 protein in the circulation of subjects with obesity and T2D." (PMID 31396158, 2019). "ANGPTL5 is an understudied member of this family that has been suggested to regulate triglyceride metabolism with a potential role in obesity." (PMID 31396158, 2019). "Given this lack of correlation between ANGPTL5 levels and both leptin and adiponectin, we suggest that the role of ANGPTL5 in obesity and T2D occurs independently of leptin and adiponectin." (PMID 31396158, 2019). "As both ANGPTL3 and ANGPTL4 are important in lipid metabolism through their interaction with lipoprotein lipase, our data suggest a role for ANGPTL5 in TGL metabolism in obesity." (PMID 31396158, 2019). "This suggests that ANGPTL5 could be a specific and a more sensitive marker for childhood as well as adult obesity than ANGPTL3 and ANGPTL8." (PMID 32286392, 2020). "Whilst we observed a positive correlation between obesity and ANGPTL5, leptin did not correlate with increasing ANGPTL5." (PMID 31396158, 2019). "The lack of significant difference in the plasma ANGPTL5 levels between normal-weight and overweight children may indicate that ANGPTL5 is a late obesity marker, and therefore, is not present in higher levels in overweight children." (PMID 32286392, 2020). "Unlike other ANGPTL proteins, the role of ANGPTL5 in developing obesity and metabolic diseases remains mostly unknown." (PMID 32286392, 2020).
Obesity (continued). "The lack of significant changes in ANGPTL5 levels between obese and non-obese subjects with T2D may be due to effect of antidiabetic medication and a conscious effort to control obesity." (PMID 31396158, 2019).
Insulin resistance (1 paper, 2019). Increased resistance towards insulin, that is, diminished effectiveness of insulin in reducing blood glucose levels. "Correlation analyses revealed that ANGPTL5 levels positively associated with fasting plasma glucose (FPG), glycated hemoglobin (HbA1c), triglycerides (TGL), and insulin resistance as measured by HOMA-IR." (PMID 31396158, 2019). "ANGPTL5 plasma levels also showed positive correlation with insulin resistance as measured by HOMA-IR." (PMID 31396158, 2019). "In our study, subjects with T2D had significantly higher ANGPTL5 plasma levels, which positively correlated with FPG, HbA1c, and insulin resistance." (PMID 31396158, 2019). "Plasma ANGPTL5 levels positively correlated with FPG (r = 0.329, P < 0.001), HbA1c (r = 0.275, P < 0.001) and insulin resistance, measured by HOMA-IR (r = 0.192, P = 0.014)." (PMID 31396158, 2019).
keloid (1 paper, 2026). An irregularly shaped, elevated mark on the skin caused by deposits of excessive amounts of collagen during wound healing. "MR indicated PIK3R3 as a causal risk factor for keloids, while ANGPTL5 showed no causal association." (PMID 41889636, 2026).
lung carcinoma (1 paper, 2015). "Further study will be necessary to determine whether other ANGPTLs, such as ANGPTL1, ANGPTL5, ANGPTL7, also enhance metastasis in lung cancer." (PMID 26056041, 2015).
mastitis (1 paper, 2021). Inflammation of breast tissue during lactation or postpartum due to an obstructed duct or infection. "Candidate genes identified in this region were related to both cell division (CEP126 (Centrosomal Protein 126)) and immune cell progenitor differentiation (ANGPTL5 (Angiopoietin like 5), supporting our theory that risk PC1 does indeed reflect both mastitis and udder and teat morphology." (PMID 33920522, 2021).
non-small cell lung carcinoma (1 paper, 2018). A group of at least three distinct histological types of lung cancer, including non-small cell squamous cell carcinoma, adenocarcinoma, and large cell carcinoma. "It has been reported that LILRB2 and ANGPTL2/ANGPTL5 were co-expressed in cancer cell lines and in primary culture of non-small cell lung cancer NSCLC." (PMID 29389861, 2018).
parasitic infection (1 paper, 2020). "Genetic variants of interest identified in several immune related genes for all the antibody response and parasitic infection traits: IBDV (TOLLIP, ANGPTL5, BCL9, THEMIS2), MDV (GRM7), SG (MAP3K21), Eimeria (TOM1L1), and cestodes (TNFAIP1, ATG9A, NOS2)." (PMID 33193617, 2020).
tumor (3 papers, 2020 to 2022). "Analysis of the Human Protein Atlas database revealed that ANGPTL2 and ANGPTL5 were highly expressed in HCC tumor tissues, while ANGPTL4 was decreased." (PMID 35692877, 2022). "The eight-gene-signature prognostic model (ANGPTL5, CD1B, CD1E, CNTFR, CTSG, EDN3, IL12B, and IL2)-based high- and low-risk groups were significantly related to overall survival (OS), tumor microenvironment (TME) immune cells, and clinical characteristics in LUAD." (PMID 34745015, 2021). "In contrast, the DNA methylation levels of ANGPTL2, ANGPTL7, and ANGPTL8 were significantly positively correlated with tumor grade, and the DNA methylation levels of ANGPTL3, ANGPTL5, and ANGPTL7 were significantly negatively correlated with age." (PMID 35692877, 2022). "ANGPTL3, ANGPTL4, ANGPTL5, ANGPTL7, and ANGPTL8 were significantly hypermethylated in tumor tissues." (PMID 35692877, 2022). "By comparing with the normal group, we found that apolipoprotein B (APOB) and carbonic anhydrase 1 (CA1) were significantly up-regulated, whereas angiopoietin like 5 (ANGPTL5) and shisa family member 7 (SHISA7) were down-regulated in the tumor samples." (PMID 33050883, 2020). "The expression level of ANGPTL5 showed a significant negative correlation with age, ANGPTL5 and ANGPTL7 showed a significant positive correlation with tumor stage, and ANGPTL7 showed a significant negative correlation with tumor grade." (PMID 35692877, 2022).
cardiovascular disease (2 papers, 2020 to 2022). "Elevated levels of ANGPTL5 were detected in obese adolescents and were associated with cardiovascular disease risk factors, high-sensitivity C-reactive protein, and oxidized low-density lipoprotein." (PMID 36293317, 2022). "In a recent study on exercise and circulating ANGPTL5 levels, the relationship between ANGPTL5 and prevalent cardiovascular disease risk factors was investigated by comparing circulating ANGPTL5 levels in obese normal-weight adolescents." (PMID 36293317, 2022). "In Conclusion, ANGPTL5 levels are elevated in obese adolescents and are associated with cardiovascular disease risk factors, HsCRP and Ox-LDL." (PMID 32286392, 2020).
heart disease (1 paper, 2013). "Six candidate genes including LMNA, Zinc Finger Homeobox 3 (ZFHX3), Matrix Metallopeptidase 2 (MMP2), Angiopoietin-Like 5 (ANGPTL5), Myosin Heavy Chain 7B (MYH7B) and Potassium voltage-gated channel subfamily H member 6 (KCNH6) have been previously linked to heart disease." (PMID 24349489, 2013).
ANGPTL5 also shares sentences with these, for which no sentence is quoted: cancer (3 papers); B-cell lymphomas (1); cervical cancer (1); metabolic disease (1); metabolic syndrome (1); Type 2 Diabetes (1).